SLFN11 (schlafen family member 11)
Diseases named in the same sentence as SLFN11 in open-access papers (continued):
Sharing a sentence is not in itself a finding about the gene and the disease.
cancer (continued). "Interestingly, existing literature suggests that hypermethylation-mediated silencing of SLFN11 and SLFN12 disrupts DNA damage recognition, impairs apoptosis, and promotes chemoresistance across multiple cancers, allowing malignant cells to persist despite therapeutic intervention." (PMID 41303540, 2025). "Indeed, AGR2 expression showed a negative correlation with SLFN11 expression in the Cancer Cell Line Encyclopedia dataset." (PMID 40459063, 2025). "Because SLFN11 functions without regard to BRCA status in a variety of settings under replication stress, we wished to elucidate the mechanism by which PARPis act when SLFN11 is expressed in BRCA deficiency cancer cells." (PMID 38961202, 2024). "Further studies are warranted to identify anticancer drugs that function specifically in SLFN11-negative cancers that could be used alone or in combination with TAK-243." (PMID 35768579, 2022). "Because SLFN11-deficient cancer cells rely on the ATR pathway to modulate their DNA replication and damage repair processes in response to replication stress, the combination of ATR inhibitors with DDAs is selectively active in SLFN11-negative cancer cells." (PMID 35768579, 2022). "Whether or not increased immune activated SLFN11 expression would actually enhance the efficacy of anti-cancer drugs is not known." (PMID 33450175, 2021). "Indeed, dichotomized SLFN11 cancer and noncancer levels were also prognostic by univariable analysis (though with smaller significance than overall SLFN11)." (PMID 34549724, 2021). "In addition, work from various groups confirmed SLFN11 as being a determinant of sensitivity to a broad range of DDAs with different modes of action, as well as PARP inhibitors, in different, mainly preclinical, cancer settings." (PMID 34549724, 2021). "Also, our findings point out that SLFN11, which is only expressed in humans and some primates, should be best assessed in clinical tissues, rather than xenograft or in vitro cancer tissues, to understand its relevance in a clinical setting." (PMID 34549724, 2021). "First, the independent prognostic value of overall SLFN11 H-score suggests that SLFN11 levels in both cancer and noncancer cells may play a role in response to platinum-containing regimens in HGSOC." (PMID 34549724, 2021). "We also found SLFN11 absent/low tumours across the different cancer types tested." (PMID 33339894, 2021). "Overall, PCA substantiated our hypothesis that high immune infiltration was driving the negative correlation of SLFN11 with cancer cellularity and that specific immune subpopulations were closely associated with high SLFN11 expression in HGSOC." (PMID 34549724, 2021). "SLFN11-low/absent cancers were identified across different tumour types tested." (PMID 33339894, 2021). "Moreover, both cancer and noncancer SLFN11 retained their independent role in stepwise multivariable models starting from the same set of variables as the one including overall SLFN11." (PMID 34549724, 2021). "SLFN11 in cancer and noncancer cells independently predicts response to platinum-based CT in HGSOC." (PMID 34549724, 2021). "Combinations of DDA with DDRi targeting the replication-stress response (ATR, CHK1 and WEE1) could re-sensitise SLFN11-absent/low cancer models to the DDA treatment and were effective in upper gastrointestinal and genitourinary malignancies." (PMID 33339894, 2021). "However, SLFN11 promoter methylation is independent of CD47 expression in some cancer types that exhibit a positive correlation between SLFN11 and CD47 mRNA expression." (PMID 31632920, 2019). "Importantly, lack of SLFN11 mRNA expression is observed in ~45% of the cancer cells in the NCI-60 and CCLE panel." (PMID 27708213, 2016). "We explored novel sensitisation strategies for DDA monotherapies in SLFN11-absent settings by combining DDA with DDRi and examined the applicability of these combinations to overcome drug resistance caused by low or absent SLFN11 protein in different cancer types." (PMID 33339894, 2021).
cancer (continued). "Similarly, SLFN11 expression was not prognostic of OS in 18/21 cancer subtypes included in TCGA." (PMID 31682620, 2019). "We also found that cancer cells that do not express SLFN11 exhibit increased global protein ubiquitylation, ER stress and UPR compared to SLFN11-proficient cells." (PMID 35903760, 2022). "Thus, we speculate that SLFN11 mRNA levels were not predictive of sensitivity to microtubule inhibitors in our study because induction of DNA damage is not the primary mechanism of anti-cancer action of these drugs." (PMID 31682620, 2019). "We did not explore SLFN11 and SLFN13 involvement in TNBC cell viability since it appeared that their expressions were controlled by SLFN12; however, that does not take away from their roles as investigated by others in cancer biology." (PMID 39594803, 2024). "The Pommier group has demonstrated that SLFN11 could inhibit stressed replication forks independent of ATR and this blockage-induced cancer cell death by SLFN11 was deemed irreversible." (PMID 38791884, 2024). "Moreover, SLFN11 absent/low tumours were present across different cancer types tested, hinting that a significant percentage of tumours might be less responsive to DDA treatment due to absent/low SLFN11." (PMID 33339894, 2021). "Accordingly, reactivation of SLFN11 expression by epigenetic drugs targeting DNA methylation, histone deacetylase (HDAC), and histone methyltransferase EZH2 (Enhancer of zeste homolog 2) can reverse the chemoresistance of cancer cell lines that do not express SLFN11." (PMID 34572827, 2021). "We believe that SLFN11 may become an essential predictive biomarker to DDA-based treatment regimens and that the combination of DDA with either WEE1i, CHKi or ATRi may be effective in treating cancers in which SLFN11 is absent or low and DDA are used as standard of care." (PMID 33339894, 2021).
tumor (74 papers, 2015 to 2026). "High expression of SLFN11 is associated with the sensitivity of tumor cells to DNA-targeted drugs, while low expression of SLFN11 is associated with the resistance of tumor cells to DNA-targeted drugs." (PMID 40766331, 2025). "In contrast, SLFN11 deficiency promoted the infiltration of immunosuppressive macrophages and aggravated tumor progression." (PMID 40766331, 2025). "At the epigenetic level, the expression of SLFN11 is regulated by promoter methylation, which is significantly associated with tumor differentiation and tumor size." (PMID 40766331, 2025). "Tumors with SLFN11-positive (SLFN11 was considered positive when at least 5% of the tumor cells were stained)were associated with longer OS p < 0.012)." (PMID 40766331, 2025). "It was found that EWS-FLI1 enhances SLFN11 expression in ES cells and SLFN11 expression was associated with increased tumor-free survival in ES patients." (PMID 40134582, 2025). "The authors of the study showed that SLFN11 expression level, as depicted by immunohistochemistry (IHC), is associated with tumor response to talazoparib in multiple patient-derived xenograft models." (PMID 40271221, 2025). "Tumors with SLFN11-positive(SLFN11 positive staining was defined as ≥15% staining of the tumor nuclei) were associated with longer PFS p < 0.001)." (PMID 40766331, 2025). "Recently, more and more studies have found that the expression status of SLFN11 is associated with the chemotherapy sensitivity of tumor patients." (PMID 40766331, 2025). "Recently, SLFN11 has been linked to the malignant phenotype of clear cell renal cell carcinoma (ccRCC) promoting tumor growth, migration, and invasion." (PMID 38791884, 2024). "The high SLFN11 expression in colorectal cancer and lung adenocarcinoma causes tumor sensitivity to irinotecan chemotherapy and platinum chemotherapy drugs." (PMID 36090985, 2022). "In summary, loss of SLFN11 increases p21 expression, blocks tumor growth and prolongs survival in an intracranial PDX model." (PMID 36382088, 2022). "On the basis of the potent biological effects of SLFN11 loss observed in vitro, we proceeded to examine KO effects on tumor cell growth in vivo." (PMID 36382088, 2022). "We find elevated tumour SLFN11 not only linked to improved clinical outcome to chemotherapy in SCLC but to an extent is also associated with olaparib sensitivity in platinum-sensitive HGSOC patients." (PMID 34663950, 2021). "To subsequently assess through which pathway SLFN11 determines the outcome of T cell recognition of tumor cells, we first exposed either SLFN11-proficient or SLFN11-deficient HAP1 cells to IFN-γ." (PMID 30753225, 2019). "SLFN11 methylation was associated with tumor diameter by univariate logistic regression analysis (p < 0.05)." (PMID 31762822, 2019). "Loss of SLFN11 promotes tumor cell proliferation by restoring ATM expression." (PMID 40766331, 2025). "Methylation of SLFN11 was also significantly associated with tumor size (p < 0.05)." (PMID 41303540, 2025). "Furthermore, in a GBM mouse model, SLFN11 deficiency significantly inhibited tumor growth and prolonged survival." (PMID 40766331, 2025). "These epigenetic processes may also induce dynamic changes in tumor expression levels of SLFN11 during chemotherapy and cause the development of acquired resistance to DDA." (PMID 35625957, 2022). "Indeed, in different tumor types, epigenetic modifications have been shown to cause loss of SLFN11 expression and associated resistance to DDA." (PMID 35625957, 2022). "Our clinical data in SCLC confirms what others have consistently shown in pre-clinical models and a small number of clinical studies, that there is an association between low SLFN11 tumour expression and resistance to directly DNA-damaging therapies, particularly in this indication." (PMID 34663950, 2021). "Methylation of SLFN11 is significantly associated with tumor size." (PMID 31762822, 2019). "Methylation of SLFN11 was significantly associated with tumor size." (PMID 31762822, 2019).
tumor (continued). "Methylation of SLFN11 was significantly associated with tumor size (p < 0.05)." (PMID 31762822, 2019). "This may tentatively suggest a potential association between tumor stage and SLFN11 expression." (PMID 40649874, 2025). "In addition, methylation may be the main reason for the decreased expression level of SLFN11, as methylation of SLFN11 leads to decreased gene expression and loss of function in tumor cells." (PMID 31514451, 2019). "SLFN11 expression is positively correlated with the abundance of various tumor-infiltrating lymphocytes (TILs), including CD4+ T cells, CD8+ T cells, macrophages, neutrophils, and dendritic cells." (PMID 40766331, 2025). "Analysis of the UALCAN database showed the mRNA level of SLFN11 was significantly positively correlated with lymph node metastasis, tumor stage and grade." (PMID 40766331, 2025). "The core mechanism is that SLFN11 can hinder DNA replication fork repair and significantly enhance the replication stress effect induced by these drugs, thereby effectively promoting tumor cell death." (PMID 40766331, 2025). "SLFN11 immunostaining of TMAs with 3,300 primary CRCs identified 65 (~2.0%) tumors with focal staining (<10% of tumor nuclei positive), 83 (~2.5%) with patchy (≥10% and <80%), and 51 (~1.5%) with diffuse (≥80%) SLFN11 positivity." (PMID 40105034, 2025). "Studies using a mouse xenograft model have shown that the re-expression of SLFN11 significantly reduces tumor weight and volume." (PMID 40766331, 2025). "In immune responses, the expression of SLFN11 enhances the effect of the IFNγ signaling pathway, making tumor cells more sensitive to cytotoxic T cells." (PMID 40766331, 2025). "Conversely, dephosphorylation restores SLFN11’s function, enhancing drug sensitivity and promoting its tumor-suppressive role." (PMID 41303540, 2025). "The study found that SLFN11 expression was significantly upregulated in tumor tissues of HCC patients who responded to ICI treatment." (PMID 40766331, 2025). "EWS models overall were the most sensitive tumor indication and as previously reported also represent a population of high SLFN11 expression, a notable biomarker of sensitization to replication associated DNA damage." (PMID 41359388, 2025). "The expression of SLFN11 is highly clinically detectable and can be reliably assessed at the mRNA or protein level in tumor tissue or circulating tumor cells (CTCs), with high concordance between the two methods." (PMID 40766331, 2025). "SLFN11 plays a pivotal role in tumor replication and growth by regulating DNA replication at replication forks." (PMID 41194225, 2025). "SLFN11 immunostaining of tumor microarrays (TMAs) with 3,300 primary CRCs identified 65 (~2.0%) tumors with focal staining (<10% of tumor nuclei positive), 83 (~2.5%) with patchy (≥10% and <80%) and 51 (~1.5%) with diffuse (≥80%) SLFN11 positivity." (PMID 40105034, 2025). "In tumor-infiltrating lymphocytes (TILs), the expression level of SLFN11 in non-tumor cells was positively correlated with the number of TILs." (PMID 40766331, 2025). "The finding that tumor expression of SLFN11 was high in the only patient with a cPR in the LMP744 trial, but negative in the other patients in the MTD cohort, is consistent with published studies." (PMID 40439882, 2025). "This suggests that SLFN11 not only affects tumor cells themselves, but is also related to the shaping of the anti-tumor immune microenvironment." (PMID 40766331, 2025). "Tumor biopsies from the patient with cPR demonstrated high baseline expression of SLFN11 and a unique pattern of pharmacodynamic responses, including increased RAD51, phosphorylated KAP1 (pKAP1), γH2AX, and cleaved caspase-3 (cCasp3)." (PMID 40439882, 2025). "The results showed a strong correlation between SLFN11 and tumor-infiltrating lymphocytes, primarily CD3+ and CD8+." (PMID 40649874, 2025). "SLFN11 inhibits tumor growth and significantly enhances the efficacy of platinum drugs by promoting S phase arrest and apoptosis." (PMID 40766331, 2025).
tumor (continued). "Schlafen 11 (SLFN11), a regulator of cell fate following DNA injury, sensitizes tumor cells to DNA‐damaging agents." (PMID 40105034, 2025). "SLFN11 expression levels change dynamically during treatment: while 70% of circulating tumor cells expressed SLFN11 in treatment-naive patients, this proportion decreased to 25% in patients receiving platinum therapy." (PMID 38790938, 2024). "Functionally, platinum treatments were specifically shown to induce tumor-immune transactivation in a SLFN11-dependent manner, suggesting that SLFN11 plays a key role in immune activation." (PMID 39588782, 2024). "SLFN11 belongs to the family of genes that play a role in cell cycle regulation, immune response, and tumor suppression." (PMID 38790938, 2024). "Under chemotherapy induction, EZH2-mediated H3K27me3 deposition in the SLFN11 gene body suppresses SLFN11 expression, thereby enhancing DNA repair efficiency, enabling tumor cell adaptation and survival." (PMID 38525426, 2024). "Pairwise comparison revealed significant differences (q ≤ 0.05) in the expression of all markers between PBMCs and tumor cells, with the exception of SLFN11 and AR-V7 between PBMCs and PC-3 cells, and EPCAM, PSA, and PSMA between PBMCs and NCI-H1299 cells." (PMID 39550585, 2024). "Zhang and colleagues showed that SLFN11 can be detected in circulating SCLC tumor cells collected from a blood draw." (PMID 38790938, 2024). "In SCLC-resistant xenograft mouse models, the EZH2 inhibitor EPZ011989 restores tumor sensitivity to irinotecan by upregulating SLFN11, and its combination with irinotecan significantly inhibits tumor growth." (PMID 38525426, 2024). "Here, we utilized two different approaches to investigate the effect of manipulating SLFN11 expression on tumor cell viability and treatment response to DNA damaging agents." (PMID 38001424, 2023). "Further understanding of the feedback loop between tumor cells SLFN11 expression and T-cells IFN-γ expression is required." (PMID 38001424, 2023). "For example, we found that the hypomethylation of the SLFN11 dDMR in LUAD was associated with higher SLFN11 expression, which was further verified in human tumour samples." (PMID 37558831, 2023). "The SLFN11 protein recently emerged as pivotal in DNA damage conditions, with predictive potential for tumor response to cytotoxic chemotherapies, particularly DDAs." (PMID 37894765, 2023). "The Schlafen 11 (SLFN11) protein has recently emerged as pivotal in DNA damage conditions, with predictive potential for tumor response to cytotoxic chemotherapies." (PMID 37894765, 2023). "We propose that early tumor screening for SLFN11 expression can aid in the selection of NSCLC patients eligible for PARPi treatment." (PMID 35511434, 2022). "Our results show that disruption of SLFN11 expression greatly impairs tumor growth and significantly improved survival in an orthotopic PDX model." (PMID 36382088, 2022). "Initially, the patient L4 TB specimen at diagnosis was classified as MET-amplified adenocarcinoma, and additional analysis showed positive neuroendocrine staining in a few tumor cells, in addition to SLFN11+ cells." (PMID 35511434, 2022). "The percentage of SLFN11 positivity was lower in tumor samples from patients with local failure after CRT than that in the corresponding primary tumors before CRT in 8 of 10 cases." (PMID 36741698, 2022). "The authors of the study with the largest number of samples were focused on the correlation of SLFN11 tumor levels with the clinical outcomes of patients treated with standard chemotherapy or olaparib maintenance." (PMID 35625957, 2022). "IHC analysis revealed that 60% of tumor cells in patient L4 TB (diagnosis and progression) were positive for SLFN11." (PMID 35511434, 2022).